TMEM39B (transmembrane protein 39B)
Description:
May protect the cells against DNA damage caused by exposure to the cold-warming stress and facilitates tissue damage repair during the recovery phase.
Synonyms: FLJ10315
Tractability: Antibody: UniProt predicts a signal peptide or a membrane-spanning region. PROTAC: ubiquitination databases record sites on it.
Gene: Protein-coding gene on chromosome 1 (32,072,031 to 32,102,866, forward strand). Ensembl gene ENSG00000121775.
Subcellular location: Endoplasmic reticulum membrane
Subcellular location (Human Protein Atlas): Vesicles
Gene Ontology:
Cellular component: endoplasmic reticulum membrane; membrane
Genetic constraint (gnomAD): Loss-of-function variants: 22 observed, 52.82 expected, observed/expected ratio (o/e) 0.42, 90% interval 0.3 to 0.6. The upper end of that interval is the gene's LOEUF score, 0.6, which puts it in group 2 of 6, group 1 being the genes least tolerant of losing a copy. Missense variants: 544 observed, 663.01 expected, observed/expected ratio (o/e) 0.82, 90% interval 0.76 to 0.88. Synonymous variants: 282 observed, 275.99 expected, observed/expected ratio (o/e) 1.02, 90% interval 0.93 to 1.13.
Homologues: Orthologues: chimpanzee TMEM39B (100% identical), macaque TMEM39B (99% identical), pig TMEM39B (99% identical), dog TMEM39B (99% identical), rabbit TMEM39B (98% identical), guinea pig TMEM39B (97% identical), mouse Tmem39b (96% identical), rat Tmem39b (96% identical), zebrafish tmem39b (75% identical), tropical clawed frog tmem39b (71% identical), Drosophila melanogaster CG13016 (26% identical), Caenorhabditis elegans tmem-39 (26% identical). Paralogues in human: TMEM39A (51% identical).
Diseases named in the same sentence as TMEM39B in open-access papers:
TMEM39B is named in the same sentence as 6 diseases in open-access papers, as found by Europe PMC text mining. Sharing a sentence is not in itself a finding about the gene and the disease. The quoted sentences say what the papers report.
glioblastoma multiforme (1 paper, 2019). "Based on BLAST, such two peptides have be accurately realigned to two specific proteins, namely, transmembrane protein 39B and fructosamine-3-kinase, contributing to the identification of glioblastoma multiforme patients." (PMID 31850330, 2019).
osteosarcoma (1 paper, 2022). A usually aggressive malignant bone-forming mesenchymal neoplasm, predominantly affecting adolescents and young adults. "Prognosis-related TMEM protein family genes were identified by the univariate Cox regression analysis and were utilized to construct a signature based on six TMEM protein family genes (TMEM120B, TMEM147, TMEM9B, TMEM8A, TMEM59, and TMEM39B) in osteosarcoma." (PMID 35991561, 2022). "In both cohorts, the expression levels of TMEM8A, TMEM39B, and TMEM59 were not related to the overall survival of osteosarcoma patients in the Kaplan–Meier survival analyses." (PMID 35991561, 2022).
cancer (1 paper, 2024). A tumor composed of atypical neoplastic, often pleomorphic cells that invade other tissues. "TMEM39b expression was significantly elevated in these cancer types, including HCC, compared to their respective normal tissues." (PMID 39055886, 2024). "The Wilcoxon rank-sum test was employed to compare the expression of TMEM39b across different cancer types using TIMER and TNMplot data." (PMID 39055886, 2024).
tumor (1 paper, 2024). "In conclusion, we propose that TMEM39b promotes tumor progression and resistance to sorafenib by inhibiting ferroptosis in HCC." (PMID 39055886, 2024).
TMEM39B also shares sentences with these, for which no sentence is quoted: hepatocellular carcinoma (1 paper); Obesity (1).